IRS1 (insulin receptor substrate 1)
Diseases named in the same sentence as IRS1 in open-access papers (continued):
Sharing a sentence is not in itself a finding about the gene and the disease.
Obesity (continued). "Enhancing GLUT4 translocation and the phosphorylation of insulin IRS‐1 and Akt are also therapeutic targets in obesity and diabetic sarcopenia [S21]." (PMID 39385717, 2024). "In the present targeted analysis of the canonical insulin signal pathway in obesity with RNAseq only one gene, IRS1, displayed statistically significant sex difference showing decreased expression in men." (PMID 38491191, 2024). "In humans and mice models, subjects with insulin resistance and obesity have decreased levels of IRS-1, IRS-2, and PI3K expression in several insulin-sensitive tissues, and of p42/p44 mitogen-activated protein (MAP) kinase in skeletal muscle." (PMID 39684905, 2024). "The downregulation of muscle PI3K transcript, but unaltered IRS-1 transcript, in the overweight cats was in agreement with another study on diet-induced obesity in cats." (PMID 39684905, 2024). "ER stress in obesity downregulates insulin receptor substrate-1 (IRS1) tyrosine phosphorylation (enhancing insulin signal inhibition) and upregulates serine IRS1 phosphorylation (inhibiting insulin signal)." (PMID 38672148, 2024). "In obesity, hyperactivation of mTORC1 induced by excessive nutrition and mitogens can lead to phosphorylation of insulin receptor substrate 1 (IRS-1) by S6K1 and negative regulation of insulin signaling by GRB10 (growth factor receptor bound protein 10)." (PMID 37511253, 2023). "Inflammation from obesity has been linked to the inhibition of the insulin receptor signaling cascade (JNK–IKK–PKR), and can target insulin receptor substrate 1 (IRS-1), causing serine phosphorylation and degradation." (PMID 35328862, 2022). "As emerged from studies performed in both human and animal models of obesity and neurodegenerative diseases, an impairment of BVR-A occurs before IRS1 inhibition and is associated with a reduced insulin signaling activation." (PMID 35628384, 2022). "Recently, interest has grown around the implication of GPx3 in obesity and IR, identifying GPx3 as a potentially novel regulator of IRS-1 expression and insulin sensitivity in WAT." (PMID 36079831, 2022). "EGR1 has been also shown to participate in IR development by causing Serine phosphorylation of IRS-1 in adipocytes and loss of EGR1 in mice protected them from obesity, IR, hyperlipedimia, and hyperinsulinemia." (PMID 35987697, 2022). "Obesity-induced inflammation and the increased secretion of adipocytokines reduces IRS-1 activation, and the AKT-dependent glucose uptake and mediated inhibition of lipolysis." (PMID 34069890, 2021). "We found that ECD delayed the development of obesity, inhibited excessive lipolysis by improving the activity of the IRS1/AKT/PKA/HSL signaling pathway in WAT of ZDF rats." (PMID 34366839, 2021). "GSK3 overactivity in obesity impairs IRS-1-dependent signaling and reduces GLUT4 translocation and glucose transport activity in the skeletal muscle." (PMID 34281282, 2021). "It is assumed that IRS1/IRS2 dysregulation plays a crucial role in the development of obesity and diabetes." (PMID 34830458, 2021). "In this study, exposure of L6 myotubes to palmitate for 16 h, to mimic the elevated FFA as often seen in obesity in vivo, resulted in significant increase in ser307 and ser636/639 phosphorylation of IRS-1." (PMID 32664532, 2020). "Endotoxins trigger inflammation by activating the TLR-4 receptor and the NF-κB pathway, which induces IRS-1 phosphorylation at serine 307 and ultimately leads to IR and obesity." (PMID 30886607, 2019). "L. lactis, Adipoq and Irs1 have been shown negatively correlated with obesity development, however, we found strongly positive correlation among relevant variables and its underling mechanism needs to be further explored." (PMID 31708891, 2019). "In wild type (WT) and PKR-/- mice, blood glucose, insulin and lipid levels and the brain expression of the phosphorylated components of the metaflammasome—PKR, JNK, IRS1 and IKKbeta—were studied after the induction of obesity by a high fat diet (HFD)." (PMID 29795582, 2018).
Obesity (continued). "In summary, we have demonstrated for the first time that maternal diet-induced obesity followed by a post-natal obesogenic diet leads to a greater reduction in IRS-1 protein expression in offspring adipose tissue than maternal obesity alone." (PMID 28338072, 2017). "Previous studies showed that obesity-induced diabetes results from defective insulin receptor-mediated signaling, which includes insulin receptor substrate 1 (IRS-1) and protein kinase B (Akt), and is also associated with increased inflammatory response." (PMID 29036927, 2017). "Elevated free fatty acids in obesity and hypoxia induce inhibitor of kappa B (IκB) kinase β (IKKβ), which phosphorylates serine residues of IRS-1 and interrupts IRS1/PI3k/Akt-dependent eNOS activity that causes NO depletion and impairment of insulin signaling." (PMID 28607631, 2017). "Levels of Irs1 mRNA were similar among all four groups suggesting that the effects of both maternal and post-weaning diet-induced obesity operate through a post transcriptional mechanism(s) to decrease IRS-1 protein levels in offspring eWAT." (PMID 28338072, 2017). "The Ser 307, Ser 636/639, Ser 616 sites on IRS-1 have been shown to be involved in insulin receptor signaling in obesity and AD." (PMID 25978724, 2015). "In fact, obesity leads to sustained activation of IRE1α that impairs insulin signaling through IRE1α/JNK-mediated phosphorylation of IRS-1 that prevents IRS-1 tyrosine phosphorylation by activated IR." (PMID 25398386, 2014). "The current study demonstrates that maternal diet-induced obesity leads to impaired adipose tissue insulin signalling in young mice of obese mothers through reduced IRβ, IRS-1 and the p110β catalytic and p85α regulatory subunits of PI3K." (PMID 24749062, 2014). "Direct evidence of IRS‐1 being the critical site of impaired insulin action in human obesity and type 2 diabetes has been elusive." (PMID 25472611, 2014). "IRS-1 is induced in high insulin conditions including the post-prandial state and obesity, whereas IRS-2 is increased in low insulin states such as fasting and caloric restriction." (PMID 22745692, 2012). "A previous study, including our group, showed that diet-induced obesity rats submitted to exercise training reduce activation of both the NF-κB and serine 307 phosphorylation of IRS-1, leading to a decreased resistance to insulin." (PMID 23046739, 2012). "Insulin resistant states such as obesity, metabolic syndrome, and DM2 cause impairment of downstream GLUT4 translocation by disruption of insulin receptor substrate-1 (IRS-1) associated PI3K signaling in the metabolic pathway of insulin." (PMID 21773024, 2011). "Activation of insulin signaling is crucial for the development of obesity and insulin receptor substrate-1 (IRS-1) transgenic mice are obese." (PMID 21738749, 2011). "This will complement obesity effects which involve simulation of inflammatory mediator IkB kinase β and phosphorylation of IRS-1." (PMID 22044490, 2011). "Both of them are important for insulin signaling within the brain: Genetic variation within the IRS-1 locus was shown to determine insulin responsiveness of the human brain and partially dysregulated IRS-2 signaling causes hyperphagia and obesity in animals." (PMID 21738722, 2011). "LAT and HAT groups were matched in age, obesity, insulin, and glucose, and had similar expression of insulin-related genes (InsR, IRS-1)." (PMID 20105310, 2010). "The gene expression of Irs1 was significantly increased by obesity (p < 0.05)." (PMID 39576482, 2025). "Similarly, EVs miR-222 inhibits the insulin receptor substrate 1 (IRS1) gene, impairing glucose uptake in skeletal muscle and hepatocytes, suggesting its potential as a therapeutic target for obesity-induced metabolic syndrome and T2D." (PMID 40001534, 2025). "Logistic regression models (LRM) and machine learning (ML) models indicated that IRS1 methylation in the placenta could strongly predict offspring obesity." (PMID 40243885, 2025).
Obesity (continued). "Finally, prediction models using both LRM and ML methods demonstrated that IRS1 methylation in the placenta strongly predicts children’s obesity." (PMID 40243885, 2025). "Similarly, obesity-associated circulating miR-222, in addition to hepatocytes, can also reach muscle cells to downregulate IRS1 and insulin signaling, thereby contributing to insulin resistance and glucose intolerance in obesity." (PMID 39769251, 2024). "Furthermore, the administration of synthetic adropin promotes glycogen synthesis, attenuates glucose production, and improves insulin sensitivity by raising IRS1/2-Akt phosphorylation and lowering the FoxO1 transcript in mouse models of diet-induced obesity." (PMID 37079136, 2023). "First, we identified gene sets related to the function of each obesity-related serum factor: HG/HI (Insr, Irs1, Rps6kb1, Slc2a4, Slc2a5, Slc2a1), TNF-α (Tnfrsf1a, Tradd, Traf2, Fadd), IL-6 (Il6ra, Il6st, Jak1), and fatty acids (PA, LA, Chol; Ffar1, Ffar4, Ppara, Pdk4, Pgc1a)." (PMID 37047207, 2023). "Obesity negatively affects insulin signaling in obese mice, as evidenced by insulin-signaling markers, including glucose transporter type 4 (Glut4) and insulin-receptor substrate 1 (Irs1), which are downregulated with HF exposure." (PMID 38137341, 2023). "Additionally, TUDCA has been shown to be helpful in obesity and diabetes by working on G protein-coupled receptors to help promote the phosphorylation of the downstream target of insulin receptor substrate 1 (IRS1), thereby improving insulin sensitivity." (PMID 37296593, 2023). "IRS1 can inhibit obesity induced by a high-fat diet through miR-503." (PMID 36672909, 2023). "In addition, SCO has a certain role in regulating obesity by regulating the Jnk-Irs1/Pi3k signaling pathways." (PMID 36766192, 2023). "The reduced tyrosine phosphorylation and increased serine/threonine phosphorylation of IRS-1 due to diabetes or obesity have mostly been considered to be negative regulators of IRS-1 function and are widely regarded as critical players in inhibiting insulin signaling." (PMID 36547071, 2022). "The expression of miR-126 was upregulated in the epididymal white adipose tissue (eWAT) of male rat offspring exposed to maternal obesity induced by diet at 8 weeks old and even at 6 months old, and its augmented expression targeted the decreasing levels of IRS-1 protein." (PMID 36438765, 2022). "Inflammation can alter insulin action and give rise to diabetes and obesity by blocking insulin receptor downstream events, impairing insulin receptor substrate 1 (IRS-1) activation and phosphatidylinositol 3-kinase-dependent (PI3K) pathways, therefore compromising insulin signaling." (PMID 33430045, 2021). "We have shown previously that maternal obesity programmes epididymal fat of young male mice offspring to overexpress miR-126-3p, resulting in impairment of the insulin signalling pathway via direct downregulation of IRS-1 protein levels." (PMID 33501603, 2021). "Specifically, IRS1 and PHGDH emerge as the DE RNAs causative of nutritional and metabolic associated diseases, as they are extremely relevant and characterized in diabetes, lipidemia, obesity (IRS1), and phosphoglycerate dehydrogenase deficiency (PHGDH)." (PMID 33924951, 2021). "The downregulation of the in vivo IRS1 levels could be due to other molecules, such as TNFα, glucocorticoid and mineralocorticoid, which are increased in obesity." (PMID 32806641, 2020). "Data from patients suffering from obesity and T2D showed reduced activity of mammalian target of rapamycin (mTOR), and lower insulin receptor substrate 1 (IRS1) levels in adipocytes from subcutaneous fat with higher autophagy activation compared with nondiabetic patients." (PMID 32015340, 2020). "Overall, our results suggest that IRS1 phosphorylation on serine 307 could be a target of interest to prevent podocyte dysfunction in a context of obesity and diabetes." (PMID 33303821, 2020).
Obesity (continued). "A link between obesity and impairment of the insulin-signaling pathway was demonstrated in a study where of mice given a high-fat diet during pregnancy resulted in offspring with both increment in body mass and adiposity also had lower levels of IRS1." (PMID 32574162, 2020). "Obesity is associated with inflammation and inflammatory cytokines including TNF-α, IL-6 and resistin promote phosphorylation of insulin receptor substrates 1 (IRS-1) at serine sites that negatively regulates normal insulin signaling." (PMID 31226166, 2019). "Hence, endothelial IRS1 can serve as a potential target to improve angiogenesis, and wound healing in patients with diabetes and obesity." (PMID 30602666, 2018). "Although we do not have suitable observation suggesting the involvement of S6K in the coffee extract-caused anti-obesity effect, it will be important to examine the influence of coffee extract on activity of S6K and CUL7, leading to the destabilization of IRS1." (PMID 28282409, 2017). "Obesity changes the secretion of adipose tissue inflammatory cytokines, which modulate insulin signaling, so we analyzed the insulin signaling gene expression including insulin receptor (IR), insulin receptor substrate 1 (IRS-1), and IRS-2 in liver tissue." (PMID 29085434, 2017). "The expression of IRS-1 in the liver appears to be relatively unaffected by obesity." (PMID 29085434, 2017). "Furthermore, coffee intake significantly prevents the HFD-induced obesity in mice and reduced the protein expression level of IRS1 in adipose tissues." (PMID 28282409, 2017). "To address this paradox, we proposed the hypothesis that Irs1-mediated insulin signalling is enhanced, whereas Irs2-mediated insulin signalling is impaired in the liver in type 2 diabetes and obesity." (PMID 27708333, 2016). "Indeed, polymorphisms of IRS1 and/or IRS2 have shown the significant associations with diabetes, glucose levels, and obesity, as well as with cancers, along with IGF signaling regulator genes." (PMID 27483248, 2016). "In addition, yerba maté inhibited hepatic Tnf-α and restored hepatic and muscle insulin signaling through an increase in IRS-1 tyrosine phosphorylation in mice with high fat diet-induced obesity." (PMID 25621503, 2015). "A programmed increase in miR-126 in response to maternal diet-induced obesity therefore provides one mechanism by which IRS-1 may be silenced at the translational level." (PMID 24749062, 2014). "Thus, as muscle IRS-1/PI3K is generally downregulated in obesity and T2DM, the activation of both Akt and aPKC in muscle is frequently diminished in these disorders." (PMID 26237474, 2014). "Mice deficient of S6K are protected against diet-induced obesity and show enhanced insulin sensitivity owing to the loss of the negative feedback loop from S6K to IRS1." (PMID 24391749, 2013). "Similarly in obesity, in intact muscle strips, there is impaired IRS-1 tyrosine phosphorylation and PI-3 kinase activity in response to insulin stimulation." (PMID 23468892, 2013). "Fat mass and obesity-associate genes (FTO) affect obesity risk and energy regulation, peroxisome proliferator-activated receptor gamma (PPARG) impacts glucose regulation and cellular differentiation, and insulin receptor substrate 1 (IRS1) modulates insulin signaling pathways." (PMID 40076293, 2025). "A murine knock-out of NE protects from obesity and shows an ameliorated metabolic phenotype including decreased triglyceride levels, smaller fat pad size, a better energy exposure, and ameliorated insulin sensitivity by decreased degradation of the insulin receptor substrate 1 (Irs1)." (PMID 38450755, 2024). "As the phosphorylation of an insulin receptor substrate 1 (IRS-1)/phosphoinositide 3-kinase (PI3K)/Akt and downstream signaling pathways, forkhead box protein O1 (FOXO1), and glycogen synthase kinase 3β (GSK3β) are modulated by THC to decrease the risk of obesity." (PMID 36263142, 2022).
Obesity (continued). "Presence of the C allele of the IRS1 gene (rs2943640) may indicate risk of high IR in type 2 diabetic patients regardless of the presence/absence of comorbid obesity and CP; here with CP is a more important factor in IR progression then obesity." (PMID 35221617, 2021). "Specifically, IRS1 and PHGDH emerge as the DE RNAs causative of nutritional and metabolic associated diseases, and these are two regulators extremely relevant and characterized in diabetes, lipidemia, obesity (IRS1), and phosphoglycerate dehydrogenase deficiency (PHGDH)." (PMID 33924951, 2021). "Moreover, a number of candidate genes previously linked through GWAS to T2DM and obesity were found to be differentially expressed in the adipose tissue from discordant twins, including PPARG, GLIS family zinc finger 3 (GLIS3) (T2DM), vascular endothelial growth factor A (VEGFA), and IRS1 (obesity)." (PMID 32653024, 2020). "Therefore, based on the close relationship between IRS1 gene and obesity and lipid metabolism, we believe that IRS1 may be a promising target for clinical prediction of O‐T2DM." (PMID 31957265, 2020). "Obesity causes ER stress that induces the UPR, which may attenuate insulin receptor signaling through hyperactivation of c-Jun N-terminal kinase and serine phosphorylation of insulin receptor substrate-1." (PMID 33066035, 2020). "IRS1 mSer612 and mSer632/635 have been cited as negative regulatory sites for IRS1 signaling through tyrosine phosphorylation, and mSer1097, regarded as a potential mammalian target of rapamycin (mTOR) /S6K signaling pathway, is activated in the liver of model animals of obesity." (PMID 31426549, 2019). "Therefore, promoter methylation was investigated at these loci, as well as at previously identified gene promoters reported in the literature to be regulated by DNA methylation in response to high-fat diet, obesity or T2D (Leptin, Pparg, Glut4, Fasn, Irs1, Hmox1, Fabp4)." (PMID 30728429, 2019). "Increased accumulation of fatty acids in tissues as seen in obesity leads serine/threonine phosphorylation of IRS proteins, resulting in a decreased signaling through reduced tyrosine phosphorylation and increased proteasomal degradation of IRS‐1 causing depression in the expression." (PMID 30680172, 2019). "Thus upregulation or overexpression of SOCS protein in obesity in the liver, muscle and adipose tissue reduces the expression of IRS1 and 2 and their tyrosine phosphorylation induced by insulin, thereby leading to insulin resistance locally in the affected tissue and systemic insulin resistance." (PMID 31738794, 2019). "Similarly, using a network-based pharmacological analysis, mulberry extracts have been proposed to regulate TNF-α, PPARγ, glycogen synthase kinase-3 beta (GSK3B), insulin receptor substrate 1 (IRS1), interleukin 6 (IL-6) and other proteins involved in diabetes and obesity associated complications." (PMID 30577684, 2018). "For example, in livers and adipose tissues of diet-induced obesity mice, overexpression of miR-103/107 negatively regulates insulin signaling by targeting Cav-1, a caveolae protein that activates insulin signaling by stabilizing the interaction between caveolae and IRS-1." (PMID 27763497, 2016). "Nevertheless, the relationship between obesity and insulin resistance is a result of changes in the insulin signal transduction pathway, with a decrease in kinase activity of insulin receptor (IR), insulin receptor substrate 1 and 2 (IRS1, IRS2), and phosphatidylinositol 3-kinase (PI3K), or both." (PMID 23046739, 2012). "Thus, if a relative increase of IRS-1 signaling is paramount in the pathogenesis of obesity comorbidities, then a pharmacologic means of restoring IRS-2 signaling might prove to be a viable therapeutic option." (PMID 22745692, 2012).